CTNNA1 (catenin alpha 1)
Diseases named in the same sentence as CTNNA1 in open-access papers (continued):
Sharing a sentence is not in itself a finding about the gene and the disease.
colorectal cancer (5 papers, 2016 to 2025). A primary or metastatic malignant neoplasm that affects the colon or rectum. "In sporadic colorectal cancer, CTNNA1 and CTNNB1 mutations are associated with younger diagnosis age (< 50 y), while patients with colorectal cancer (CRC) with CTNNA1 mutations have considerably increased lymph node metastasis." (PMID 36741258, 2023). "Our findings add a new regulatory circuit via competing endogenous RNA (ceRNA) cross-talk between pseudogene CTNNAP1 and its cognate gene CTNNA1, and provide new insights into potential diagnostic biomarker for monitoring human colorectal cancer." (PMID 27487124, 2016). "In the study, we demonstrated that pseudogene CTNNAP1, for the CTNNA1 gene, was dysregulated in colorectal cancer and the degree of dysregulation was remarkably associated with tumor node metastasis (TNM) stage (P<0.05)." (PMID 27487124, 2016). "A study using a tumor metastasis PCR array found CTNNA1 to be upregulated in PDAC cancer metastasis, while another study on colorectal cancer found the downregulation to be associated with a more aggressive phenotype." (PMID 38927982, 2024). "This suggests that low CTNNA1 expression correlates with lymphatic metastasis, poor differentiation, and poor prognosis of colorectal cancer." (PMID 36741258, 2023). "This is different from the phenomenon in which positive CTNNA1 expression is detected in metastatic lesions of colorectal cancer." (PMID 36741258, 2023). "Immunohistochemistry assays reveal that CTNNA1 expression is decreased in colorectal cancer (32/82) compared with that in normal colorectal mucosa and colorectal adenoma (8/10)." (PMID 36741258, 2023). "In the current study, we demonstrated for the first time that lower expression of pseudogene CTNNAP1 resulted in CTNNA1 mRNA level suppression by microRNA-141, and conferred a malignant phenotype to colorectal cancer cells lines." (PMID 27487124, 2016). "Therefore, CTNNA1 plays a role as a tumor suppressor gene in colorectal cancer by inhibiting the Wnt pathway." (PMID 36741258, 2023). "Chen X uncovered the role of pseudogene CTNNAP1 and its cognate gene CTNNA1 in colorectal cancer." (PMID 30337839, 2018). "Therefore, CTNNA1 may maintain the polarization state of cells in colorectal cancer, which in turn maintains the epithelioid morphology of cancer cells via regulating K-Ras phosphorylation." (PMID 36741258, 2023). "However, CTNNA1 plays an inhibitory role in advanced colorectal cancer, which may be related to the Wnt and K-Ras pathways, although the specific mechanism remains unknown." (PMID 36741258, 2023). "The results showed that, compared with normal tissues, the expression of ADRA1B, CDKN2A, FCER2, and IL13 was significantly upregulated in colorectal cancer tissues, while CALM1, CTNNA1, GSR, INSR, and MAPK9 were significantly downregulated." (PMID 40696679, 2025). "Three-dimensional culture technology has shown that CTNNA1 represses cell adhesion and invasion but has no impact on the sensitivity of colorectal cancer cells to chemoradiotherapy." (PMID 36741258, 2023).
acute myeloid leukemia (4 papers, 2012 to 2023). Acute myeloid leukemia (AML) is a group of neoplasms arising from precursor cells committed to the myeloid cell-line differentiation. "While CTNNA2 has been found as hub for extracellular matrix organization, loss of CTNNA1 is exhibited by multiple cancer types, and restoration of CTNNA1 expression in acute myeloid leukemia cells led to lower proliferation." (PMID 29052507, 2017). "The aim of this study is to evaluate the frequency of CTNNA1 hypermethylation in acute myeloid leukemia (AML) patients in an attempt to improve molecular prognostic model." (PMID 27129146, 2016).
gastric adenocarcinoma (3 papers, 2021 to 2025). "IHC revealed the loss of catenin alpha-1 expression in the gastric adenocarcinoma and preserved catenin alpha-1 expression in the normal epithelial structures." (PMID 37686589, 2023).
myeloid malignancies (3 papers, 2011 to 2016). "Our results implicating a transforming role for sub-haploinsufficient levels of MYBL2 build upon earlier studies implicating progressive inactivation of CTNNA1 and the graded reduction of PU.1 expression in the molecular pathogenesis of myeloid malignancies." (PMID 23878725, 2013). "Thus, we sought to identify candidate tumor suppressor genes within the 20q CDR on the basis of their reduced expression in malignant myeloid progenitor cells for CTNNA1 in myeloid malignancies with deletions of chromosome 5q." (PMID 23878725, 2013). "CTNNA1 hypermethylation in AML patients has been reported over the years, however the associations with expected gene aberrations that are frequently detected in myeloid malignancies, as well as clinical impact, has not been elaborated." (PMID 27129146, 2016).
ovarian carcinoma (3 papers, 2017 to 2023). A malignant neoplasm originating from the surface ovarian epithelium. "Five hypermethylated genes (CD97, CTNNA1, DLC1, CD97, and HAPLN2) and three hypomethylated genes (LAMA4, LPP, and MFAP4) are significantly associated with poor recurrence-free survival of ovarian cancer tissues from TCGA (n = 391) using multivariate Cox regression analysis." (PMID 36741258, 2023). "CTNNA1 hypermethylation is also present in endometrial and ovarian cancers, however the specific impact of CTNNA1 hypermethylation on progression and prognosis of these types of tumors remains unclear." (PMID 36741258, 2023). "Two genes (CTNNA1, CDKN1C) are common in breast and ovarian cancers." (PMID 31205821, 2019). "Furthermore, our results focused on methylation status of CAMs and revealed a 3-gene (CTNNA1, DLC1, MFAP4) methylation signature with a prognostic significance that may provide a new biomarker for personalized treatment in ovarian cancer." (PMID 28881822, 2017).
pancreatic cancer (3 papers, 2023). "This suggests that CTNNA1 may be associated with tumorigenesis or metastasis in pancreatic cancer." (PMID 36741258, 2023). "In pancreatic cancer, ablation of SETD2 caused the deletion of CTNNA1, thereby mediating the enhancement of EMT, which strongly suggests that CTNNA1 plays a role in suppressing EMT." (PMID 36741258, 2023). "A group of pancreatic cancer cells with high metastasis had over 40 differentially expressed genes (including CTNNA1) with liver metastasis tissues of pancreatic cancer; this was three times more than untreated cells." (PMID 36741258, 2023). "CTNNA1 inhibits tumor metastasis and cell growth through inhibition of EMT in bladder cancer, and the reversal of the oncogenic effect of EMT by miR-429 and Setd2 in colorectal and pancreatic cancers is also associated with CTNNA1." (PMID 36741258, 2023). "Moreover, survival analysis shows that pancreatic cancer patients with high expression of CTNNA1, CTNNB1, or CTNND1 have a poor prognosis." (PMID 36741258, 2023). "CTNNA1, CTNNB1, and CTNND1 are key molecules potentially involved in pancreatic cancer metastasis mediated by hsa-miR-30d-5p/GJA1." (PMID 36741258, 2023). "Predicted to be targeted by miR409, Catenin Delta 1 (CTNND1) along with Catenin alpha 1 (CTNNA1) and Catenin Beta 1 (CTNNB1) expression was shown to indicate a poor prognosis for pancreatic cancer patients." (PMID 36983764, 2023). "CTNNA1 is a key component of the E-cadherin adherens junction while ARHGEF10 is a GTP exchange factor for RhoGTPases with in vitro studies demonstrating increased cell motility and invasiveness in ARHGEF10 depleted pancreatic cancer cells." (PMID 37973922, 2023).
Right ventricular cardiomyopathy (3 papers, 2016 to 2021). Right ventricular dysfunction (global or regional) with functional and morphological right ventricular abnormalities, with or without left ventricular disease. "It was found in key genes related to diabetic nephropathy that CTNNA1 factor can cause other arrhythmogenic right ventricular cardiomyopathy." (PMID 33494823, 2021). "The pathways involved in the antagonistic GSK-126 group were the bacterial invasion of epithelial cell pathway and the arrhythmogenic right ventricular cardiomyopathy (ARVC) pathway, involving proteins of the PSMD family such as CTNNB1, CTNNA1, PHB1, and SUCLG2." (PMID 33195195, 2020).
cardiomyopathy (2 papers, 2016 to 2024). A disease of the heart muscle or myocardium proper. "Upregulated genes linked to cardiomyopathy included Pkp2, Dst, Dsg2 and Jup; downregulated genes included Pkp1, Dsg1a, Pkp4, Vcl, Gja1 and Ctnna1." (PMID 26935106, 2016). "Catenin Alpha 1 (CTNNA1) is integral to the cadherin-catenin complex, crucial for cell-cell adhesion, with disruptions in its function or phosphorylation potentially leading to cardiomyocyte detachment and unique forms of cardiomyopathy and increased vulnerability to fatality after cardiac stress." (PMID 38559672, 2024).
endometrial cancer (2 papers, 2022 to 2023). Primary or metastatic malignant neoplasm involving the endometrium (mucous membrane that lines the endometrial cavity). "Positive expression of CDH1, CTNNA1, and CTNNB were associated with good prognosis for endometrial cancer 67 and correlated with FIGO stages I-II (P = 0.02)." (PMID 36741258, 2023). "Current studies have identified reduced CTNNA1 expression in many types of tumors, including colorectal, breast and endometrial cancers." (PMID 36741258, 2023). "In addition, we can see that the endometrial cancer pathway directly related to tumor development contains three genes of QKI, CTNNA1, GSK-3b." (PMID 35068348, 2022).
leukemia (2 papers, 2016 to 2023). A malignant (clonal) hematologic disorder, involving hematopoietic stem cells and characterized by the presence of primitive or atypical myeloid or lymphoid cells in the bone marrow and the blood. "CTNNA1 is abnormally expressed in leukemia and solid tumor such as cancers of digestive system, genitourinary system and breast, and it's related to the occurrence, development, and prognosis of tumors." (PMID 36741258, 2023). "In recent years, a few studies have shown that CTNNA1 is expressed in normal hematopoietic stem cells (HSCs); however, its expression is significantly lower in human leukemia initiating cells (LICs) in AML." (PMID 27129146, 2016). "CTNNA1, shown to act as a leukemia-suppressor gene, played a vital role in normal hematological cell development and differentiation." (PMID 27129146, 2016). "Current reviews on the role of CTNNA1 in malignancies are limited mainly to HDGC 50, 53, 65, 90, 91; however, this review covers the pathogenesis of multisystem solid tumors and leukemia." (PMID 36741258, 2023). "A chromosomal inhibition marker (H3K27me3) is detected at the CTNNA1 promoter in AML, or primary leukemia, with CTNNA1 inhibition, and the most inhibited state is associated with CTNNA1 hypermethylation." (PMID 36741258, 2023).
lung carcinoma (2 papers, 2012 to 2021). "The HIF, TGM2, CSNK1A1, CSNK2A1, CTNNA1, NAMPT)/Visfatin, TNFRSF1A, ETS1 and SRC-1 were down-regulated and proposed as the biomarkers for lung cancer." (PMID 23122428, 2012). "Expression analysis reveals that hypoxia induced lung cancer related biomarkers, HIF and its modulating proteins (TGM2, CSNK1A1, CTNNA1, NAMPT/Visfatin, TNFRSF1A, ETS1, SRC-1, FN1, APLP2, DMBT1/SAG, AIB1 and AZIN1) are significantly down regulated." (PMID 23122428, 2012).
Lynch syndrome (2 papers, 2022 to 2025). An autosomal dominant hereditary neoplastic syndrome characterized by the development of colorectal carcinoma and a high risk of developing endometrial carcinoma, gastric carcinoma, ovarian carcinoma, renal pelvis carcinoma, and small intestinal carcinoma. "Among these 45 patients, 11 out of the 16 with diffuse tumours fulfilled the HDGC criteria for testing the CDH1/CTNNA1 genes, and two of these 11 also fulfilled the criteria for Lynch syndrome (both with a pathogenic variant in the MLH1 gene)." (PMID 40446793, 2025).
retinal disease (2 papers, 2019 to 2021). "The retinal disease phenotype of the presented case exhibits features consistent with late-onset PD, including a butterfly-like central lesion associated with PRPH2 and, more recently, recessive mutations in CTNNA1." (PMID 30630813, 2019).
Retinal dystrophy (2 papers, 2021 to 2025). Retinal dystrophy is an abnormality of the retina associated with a hereditary process. "While the variable phenotype and natural history of PRPH2- and OTX2-associated retinal dystrophies have been described in large cohorts, clinical features of CTNNA1-associated retinal dystrophy are less well studied." (PMID 40455352, 2025). "Further research to understand how these variants lead to RPE and rod photoreceptor dysfunction are critical for informing the development of effective therapeutic interventions for CTNNA1-associated retinal dystrophy." (PMID 40455352, 2025). "CTNNA1-associated retinal dystrophy due to p.(Leu318Ser) has a unique peripheral retinal phenotype despite variable macular involvement." (PMID 40455352, 2025). "This study expands the CTNNA1-associated retinal dystrophy spectrum to include enlarging paracentral scotoma from butterfly-shaped pigment dystrophy and functionally significant peripheral reticular pigmentary changes." (PMID 40455352, 2025). "A more recent report found a heterozygous missense variant (p.S322L) in CTNNA1 in a female patient with retinal dystrophy." (PMID 33435129, 2021). "Another WES study reported a heterozygous missense variant (p.G353C) in CTNNA1 in a patient affected by Leber’s congenital amaurosis with rapid and severe vision loss due to retinal dystrophy." (PMID 33435129, 2021). "CTNNA1-associated retinal dystrophy also lacks ADVIRC-associated features such as microcornea, shallow anterior chamber, iris dysgenesis, macular oedema, optic nerve dysplasia, progressive generalised atrophy and severe ERG abnormalities distinguishing it from BEST1-related ADVIRC." (PMID 40455352, 2025). "Peripheral retinal changes in CTNNA1-associated retinal dystrophy are not well characterized." (PMID 40455352, 2025).
Sepsis (2 papers, 2025). Sepsis is defined as life-threatening organ dysfunction caused by a dysregulated host response to infection. "To refine candidate selection, we implemented machine learning algorithms (random forest and SVM-RFE), which robustly identified TMCC2, TNFSF10, and CTNNA1 as key predictors of sepsis severity." (PMID 40362669, 2025). "Mechanistically, RNA pull-down and RNA RIP assays demonstrated that hsa_circ_0074158 directly binds to the RNA-binding protein (RBP) EIF4A3, which decreases the stability of CTNNA1 (mRNA) and the production of α-catenin, subsequently impairing endothelial barrier function in sepsis." (PMID 41058681, 2025). "Genes such as TMC2, TNFSF10, and CTNNA1 were the most significant predictors of sepsis severity." (PMID 40362669, 2025).
arrhythmogenic right ventricular cardiomyopathy (1 paper, 2016). "Besides, some other ones were correlated with arrhythmogenic right ventricular cardiomyopathy (e.g. ACTN4, CTNNA1 and ITGB5), as well as complement and coagulation cascades (e.g. C1R and C1S)." (PMID 27613243, 2016).
autism (1 paper, 2019). Persistent deficits in social interaction and communication and interaction as well as a markedly restricted repertoire of activity and interest as well as repetitive patterns of behavior.
bladder cancer (1 paper, 2023). "The inhibitory effect of CTNNA1 in bladder cancer was implicated in enhancing CDH1 expression and inhibiting EMT." (PMID 36741258, 2023). "The discovery that low CTNNA1 expression is associated with a higher degree of bladder cancer progression, accompanied with the discovery that the CTNNA1 pathway exists in the exosomes of bladder cancer cells, will facilitate future studies on CTNNA1 in other cancer types." (PMID 36741258, 2023). "CTNNA1 enhances the expression of CDH1 and inhibits the expression of CDH2, SNAI1, MMP2, and MMP9 in bladder cancer cells." (PMID 36741258, 2023).
blepharocheilodontic syndrome (1 paper, 2023). An ectodermal dysplasia syndrome characterized by the association of abnormalities of the eyelids, lips, and teeth. "Beyond HDGC predisposition, the CTNNA1 and CDH1 genes have been associated with macular dystrophy patterned and cleft lip/palate and blepharocheilodontic syndrome (BCD), respectively." (PMID 37686589, 2023).
breast ductal carcinoma (1 paper, 2023). "In addition, CTNNA1 re-expression obtained in the corresponding lymph node metastases is a common event in breast ductal carcinoma and plays a central role during the establishment of metastasis." (PMID 36741258, 2023).
depression (1 paper, 2024). "Another study also confirmed increased transcription of TJP1/ZO-1 and CTNNA1 in the dACC of suicidal patients with depression compared to psychiatrically normal controls." (PMID 38891940, 2024).
esophageal cancer (1 paper, 2023). A primary or metastatic malignant neoplasm involving the esophagus. "The gene expression of high-risk HPV (human papillomavirus) infection-related esophageal cancer is different compared to that of low-risk HPV; for example, CTNNA1 expression decreases in esophageal cancer." (PMID 36741258, 2023).
Esotropia (1 paper, 2021). A form of strabismus with one or both eyes turned inward ('crossed') to a relatively severe degree, usually defined as 10 diopters or more. "Finally, a missense variant in CTNNA1 (Catenin α 1) was observed across multiple cases in Family 15, characterized by comitant esotropia (I.2, II.1, and III.1)." (PMID 33435129, 2021).
Familial adenomatous polyposis (1 paper, 2023). Familial adenomatous polyposis (FAP) is characterized by the development of hundreds to thousands of adenomas in the rectum and colon during the second decade of life. "Almost all intestinal adenomas from familial adenomatous polyposis (FAP) mouse lines that carry a truncation mutation at codon 580 in adenomatous polyposis coli (Apc580D) have both CTNNA1 and adenomatous polyposis coli (APC) gene deletions." (PMID 36741258, 2023).
gastric tumors (1 paper, 2023). "We also performed IHC in gastric tumors of ten index cases from this series known to be wild-type for the CDH1 and CTNNA1 genes and for whom tumor specimens were available, and catenin alpha-1 expression was retained in both normal and tumor cells." (PMID 37686589, 2023).
gynecological cancers (1 paper, 2023). "CTNNA1, CTNNB1 and CDH1 expressions were found to be suppressed in EC as well as other gynecological cancers, and further decreased with advanced invasion, contributing to cell-to-cell junctional dysfunction." (PMID 37313172, 2023).
intestinal cancer (1 paper, 2023). "Therefore, the mutation status of CTNNA1 is essential for intestinal cancer." (PMID 36741258, 2023).
lymph node metastases (1 paper, 2023). "Meanwhile, CTNNA1 expression decreases or is very low in lymph node metastases (6/10)." (PMID 36741258, 2023).
melanoma (1 paper, 2021). A malignant, usually aggressive tumor composed of atypical, neoplastic melanocytes. "On the other hand CYT-low metastatic melanomas had recurrent amplifications in loci 5p15.33 (TERT), 6p25.1 (CDYL), 7p22.2 (RAC1), 12q15 (MDM1) and recurrent deletions in 5q31.2 (CTNNA1, FGF1), 11q22.3 (FDX1, RDX, ZC3H12C), and 15q14 (RASGRP1, CSNK1A1P1, SPRED1)." (PMID 33779796, 2021).